GOLM1 (golgi membrane protein 1)
Diseases named in the same sentence as GOLM1 in open-access papers (continued):
Sharing a sentence is not in itself a finding about the gene and the disease.
cancer (continued). "Analysis of affected individuals belonging to high‐risk pedigrees has long been a powerful design for identification of rare cancer predisposition genes and variants in Utah (e.g., BRCA1 [OMIM 113705], BRCA2 [OMIM 600185], CDKN2A [OMIM 600160], GOLM1 [OMIM 606804], APC, PTEN [OMIM 601728])." (PMID 33118316, 2020). "Golgi membrane protein 1 (GOLM1) has been identified as a novel regulator in a variety of cancers, yet its role in LSCC remains unclear." (PMID 32850310, 2020). "The activation of mTOR signaling pathway stimulated by Golgi membrane protein 1 (GOLM1) overexpression in BMSCs was in sympathy with that in cancer cells, behaving inhibited osteogenic differentiation of BMSCs due to increased GDH activity and glutamine to α-KG conversion." (PMID 31611919, 2019). "Therefore, elucidation of the regulatory networks of GOLM1-mediated signaling pathways will provide important information for the development of new therapeutic strategies against cancer cell metastasis." (PMID 25115396, 2014). "Because the transcription of a chimeric RNA generated by read-through/splicing is controlled by the promoter of the 5' parental gene, the higher level of chimera in cancer raised the question if this is because that the 5' parental genes (GOLM1) is over-expressed in ESCC?" (PMID 24243830, 2013). "However, while a number of studies have demonstrated that GOLM1 is expressed in cancer cells, the exact molecular mechanisms mediating GOLM1 function remain unclear." (PMID 25115396, 2014). "Some studies have found that in mouse intestinal epithelial cells, the lack of Golgi membrane protein 1 causes abnormal activation of Notch, thus affecting the differentiation and maturation of intestinal epithelial cells, leading to the occurrence and development of malignant tumors." (PMID 39691600, 2024). "It has been determined that Golgi membrane protein 1 (GOLM1), which is abundantly expressed in PCa, is a key factor for EMT in several cancers." (PMID 38745115, 2024). "The examination of GOLM1 and B4GALT1 gene expression in PAAD cancer was conducted using Gene Expression Profiling Interactive Analysis (GEPIA)." (PMID 38608280, 2024). "Golgi phosphoprotein 73 (GP73, also termed as GOLM1 or GOLPH2) is a glycosylated protein residing on cis-Golgi cisternae and highly expressed in various types of cancer tissues." (PMID 34950590, 2021). "Golgi Membrane Protein 1 (GOLM1), a protein involved in the trafficking of proteins through the Golgi apparatus, has been shown to be oncogenic in a variety of human cancers." (PMID 29282077, 2017). "Thus, GOLM1, a multifunctional protein, plays an essential role in facilitating cancer cells’ epithelial-mesenchymal transition (EMT) and inducing cancer metastasis." (PMID 36499755, 2022). "A recent study has discovered that mTOR upregulates GP73 through reducing the level of miR-145, the miRNA targeting 3′UTR of GOLM1, and exosomal GP73 facilitated proliferation and invasion of neighboring cancer cells by upregulating glycogen synthase kinase-3β (GSK-3β) and MMPs." (PMID 34950590, 2021). "We obtained a six-gene signature (APOBEC3B, GOLM1, FAM117A, KCNQ1OT1, PCDHB2, and USP43) with the ability to predict overall survival and progression-free survival (PFS), which could translate into a prediction of the response to the cancer treatment received." (PMID 35565183, 2022). "The multiple factors involved in the resistance of cancer cells to methotrexate also participate in complex extracellular signal pathways, e.g., GOLM1 is a positive regulator of the PI3K/AKT pathway, and the PI3K inhibitor BKM120 abrogates the function of GOLM1 during the oncogenic process." (PMID 34208465, 2021).
infection (11 papers, 2013 to 2025). The state of being infected such as from the introduction of a foreign agent such as serum, vaccine, antigenic substance or organism. "Expression of Tgfbr1, Hexb, Golm1, and Sall1 increase with microglia maturity, and maturation is dependent on TGF-β signaling which was up-regulated by maternal infection." (PMID 38730262, 2024).
intestinal diseases (2 papers, 2021 to 2025). "GOLM1 knockout in IECs disrupted intestinal homeostasis and aggravated intestinal disorders via activating excessive Notch signaling." (PMID 33850109, 2021).
GOLM1 also shares sentences with these, for which no sentence is quoted: Cirrhosis (36 papers); liver cirrhosis (15); autoimmune hepatitis (10); renal cell carcinoma (9); fibrosis (8); chronic hepatitis (6); chronic hepatitis B (6); gastric cancer (6); alcoholic liver diseases (5); COVID-19 (5); Hyperglycemia (5); Acute hepatitis (4); adenocarcinoma (4); adenovirus infection (4); hepatitis B (4); inflammation (4); non-alcoholic fatty liver disease (4); non-small cell lung carcinoma (4); seminoma (4); bile duct carcinoma (3); dyslipidemia (3); Obesity (3); steatosis (3); viral hepatitis (3); adenocarcinomas of prostate (2); Alzheimer disease (2); Chronic Hepatitis C (2); cutaneous melanoma (2); esophageal cancer (2); Hepatic steatosis (2).
A further 64 diseases each share a sentence with GOLM1 in 2 papers or fewer.